SLC7A11 (solute carrier family 7 member 11)
Diseases named in the same sentence as SLC7A11 in open-access papers (continued):
Sharing a sentence is not in itself a finding about the gene and the disease.
diabetic cardiomyopathy (4 papers, 2022 to 2026). Diabetic cardiomyopathy is a disorder of the heart muscle in people with diabetes. "Advanced glycation end-products, an important pathogenic factor in diabetic cardiomyopathy, were found to induce ferroptosis in engineered cardiac tissues by downregulating SLC7A11 levels." (PMID 35992146, 2022). "Ferroptosis was also evident in the heart of diabetic cardiomyopathy associated with the downregulation of SLC7A11 signaling." (PMID 35992146, 2022). "Collectively, high-dose ALA suppresses ferritinophagy and activates the SLC7A11/GSH/GPX4 antioxidant axis via the AMPK-STAT3 signaling pathway to alleviate ferroptosis-induced diabetic cardiomyopathy." (PMID 41515376, 2025). "Interestingly, Nrf2 activated by sulforaphane was shown to suppress cardiac cell ferroptosis in both AGE-treated ECTs and the hearts of diabetic cardiomyopathy mice by upregulating ferritin and SLC7A11." (PMID 36980208, 2023).
diabetic nephropathy (4 papers, 2022 to 2026). "In diabetic nephropathy renal biopsies, ferroptosis-related molecules SlC7A11 and GPX4 expression were reduced compared to in non-DN patients." (PMID 36432138, 2022).
endotoxemia (4 papers, 2007 to 2024). "Given the specific Slc7a11 upregulating properties of LPS, we induced endotoxemia by injection with 2mg/kgbw LPS in WT and KO mice and harvested peritoneal lavage 2 hours after induction to measure intracellular cytokines." (PMID 37792774, 2023).
Hyperglycemia (4 papers, 2021 to 2025). An increased concentration of glucose in the blood. "Chronic hyperglycemia disrupts the cystine/SLC7A11/glutathione axis, accelerating neuronal degeneration and linking DM to PD susceptibility." (PMID 40613317, 2025). "Chronic hyperglycemia disrupts the cystine/SLC7A11/glutathione axis, impairing cystine uptake and depleting glutathione in dopaminergic neurons, increasing ferroptosis susceptibility." (PMID 40613317, 2025). "However, absence of SESN2 did not completely inhibit the effect of Mg2+ on endothelial cells under hyperglycemia, suggesting other regulatory mechanisms such as ATF4 or SLC7A11 might make an impact." (PMID 38296940, 2024).
liver diseases (4 papers, 2021 to 2026). "Thus, more experimental studies are merited to further elucidate in what way epigenetic modification of PHGDH and SLC7A11 could explain the beneficial effect of coffee consumption on lipid metabolism and liver diseases." (PMID 33990564, 2021).
mastitis (4 papers, 2025). Inflammation of breast tissue during lactation or postpartum due to an obstructed duct or infection. "In conclusion, GAP may inhibit S. aureus-induced mastitis in mice by triggering the Nrf2/SLC7A11/GPX4 signaling pathway and alleviating inflammation and ferroptosis." (PMID 39612214, 2025). "In mice with mastitis induced by Staphylococcus aureus, the expression of NRF2 is significantly inhibited, and the expression of downstream target proteins (including SLC7A11 and GPX4) decreases, leading to ferroptosis and aggravated mastitis." (PMID 41413615, 2025).
memory impairment (4 papers, 2022 to 2025). "qRT-PCR revealed that GPX4 and SLC7A11 gene expression were dramatically downregulated in the hippocampus of CCI with memory impairment model rats 21 days." (PMID 35547819, 2022). "Furthermore, the protein expressions of GPX4 and SLC7A11 in the hippocampus of CCI with memory impairment model rats 21 days were all considerably reduced, according to the western blot." (PMID 35547819, 2022). "We also discovered that ATF3 was considerably overexpressed in the hippocampal CA1 area, and gene markers of ferroptosis, such as GPX4, SLC7A11, SLC1A5, and PTGS2, were dysregulated in the CCI-induced memory impairment paradigm." (PMID 35547819, 2022). "qRT-PCR revealed that in the hippocampus of CCI with memory impairment model rats 21 days after Fer-1 therapy, GPX4 and SLC7A11 gene expressions were dramatically increased." (PMID 35547819, 2022). "Moreover, we found the expression of SLC7A11 and GPX4 in the hippocampus of CCI-induced memory impairment using western blot." (PMID 35547819, 2022). "Similarly, lipid peroxidation and gene markers (GPX4, SLC7A11, SLC1A5, and PTGS2) dysregulation of ferroptosis were discovered in the CCI-induced memory impairment model." (PMID 35547819, 2022).
mesothelioma (4 papers, 2021 to 2024). A usually malignant and aggressive neoplasm of the mesothelium which is often associated with exposure to asbestos. "Interestingly, we further found that high expression of SLC7A11 were significantly associated with shortened OS and disease-free survival of KIRP, LIHC, and MESO (mesothelioma), and high expression of GPX4 was significantly correlated with shortened OS and disease-free survival of STAD." (PMID 34722530, 2021).
multiple myeloma (4 papers, 2016 to 2025). "Elevated SLC7A11 expression in myeloma cells increases susceptibility to erastin-induced ferroptosis." (PMID 40007539, 2025). "For example, in cases of multiple myeloma, cells that express high levels of SLC7A11 showed increased sensitivity to ferroptosis induced by erastin, highlighting the complex role of SLC7A11 in influencing cell fate when faced with therapeutic challenges." (PMID 40535572, 2025).
Myocardial fibrosis (4 papers, 2023 to 2025). "Drugs that reduce myocardial fibrosis are associated with increased SLC7A11 expression within cardiomyocytes and reduced ferroptosis." (PMID 40249927, 2025). "Thus, the association between SLC7A11 and myocardial fibrosis is unclear." (PMID 40249927, 2025). "Therefore, future research should explore the effect of SLC7A11 on cardiomyocyte ferroptosis beyond conventional drug treatments with unclear targets and focus on investigating its specific role in fibrotic diseases by investigating the mechanisms underlying myocardial fibrosis." (PMID 40249927, 2025). "Myocardial fibrosis, accompanied by ferroptosis and SLC7A11 downregulation, has also been observed in canine models of atrial fibrillation and rat H9C2 cells." (PMID 40249927, 2025). "Considering the diverse effects of SLC7A11 in different cell types and their intricate interactions within cardiac tissue would lay a solid foundation for future drug development to treat myocardial fibrosis." (PMID 40249927, 2025). "Dexmedetomidine treatment inhibits ferroptosis and upregulates SLC7A11, thereby reducing myocardial fibrosis." (PMID 40249927, 2025). "In a murine model of ischemia-reperfusion-induced myocardial fibrosis, myocardial fibrosis was concomitant with ferroptosis and SLC7A11 downregulation." (PMID 40249927, 2025). "Nonetheless, SLC7A11 expression confers protection against myocardial fibrosis, making it a potential target for future therapeutic interventions." (PMID 40249927, 2025). "Additionally, xCT knockout mice exhibit increased fibrosis under same triggers, providing strong evidence that SLC7A11 plays a protective role in preventing myocardial fibrosis." (PMID 40249927, 2025). "The precise mechanism by which SLC7A11 protects against myocardial fibrosis remains unclear, and further research is warranted." (PMID 40249927, 2025). "Yueet al. reported significantly reduced SLC7A11 and GPX4 expressionin AF patients, reaffirming the integral role that ferroptotic activity plays inAF-related myocardial fibrosis and suggesting that such activity is mediated bythe xCT/GPX4 pathway." (PMID 39076535, 2024).
osteoarthritis (4 papers, 2023 to 2025). A noninflammatory degenerative joint disease occurring chiefly in older persons, characterized by degeneration of the articular cartilage, hypertrophy of bone at the margins and changes in the synovial membrane.
rectal cancer (4 papers, 2022 to 2025). A primary or metastatic malignant neoplasm that affects the rectum. "Meanwhile, SLC7A11 also affects the infiltration of immune cells in rectal cancer, such as CD8+ T cells." (PMID 35517862, 2022). "TCGA analysis further confirmed that SLC7A11 is upregulated in both colon and rectal cancers." (PMID 41213937, 2025). "Several recent studies have confirmed that YTHDF2 can inhibit the expression of SLC7A11 and SLC3A2 through m6A modification, which in turn regulates ferroptosis in rectal cancer cells." (PMID 40948766, 2025).
retinal degeneration (4 papers, 2021 to 2025). Degeneration of the retina. "As a key amino acid transporter, SLC7A11’s reduced activity is closely associated with decreased glutathione (GSH) levels, leading to increased oxidative stress in retinal cells and accelerating retinal degeneration." (PMID 39634176, 2024). "The induction of Slc7a11 expression in the retina by NK-4 may enhance the antioxidant activity to reduce retinal degeneration." (PMID 34358120, 2021). "Our results demonstrate that LCN2 induced ferroptosis in light-induced retinal degeneration by increasing the Fe2+ level and promoting the activation of JNK, and subsequent inhibition of the SLC7A11-GSH-GPX4 axis." (PMID 40375133, 2025). "Therefore, SLC7A11 and MYC may directly or indirectly promote retinal degeneration by affecting metabolism, antioxidant defense, cell proliferation, and apoptosis." (PMID 39634176, 2024). "Therefore, the upregulation of the SLC7A11/GSH/GPX4 axis in RPE cells may be one of the PEDF‐mediated antioxidant mechanisms to counteract the pathogenesis of oxidative stress‐induced RPE damage and retinal degeneration." (PMID 40703032, 2025).
sarcopenia (4 papers, 2021 to 2026). Progressive decline in muscle mass due to aging which results in decreased functional capacity of muscles. "The downregulation of Slc7a11 then induced the ferroptosis of muscle cells through the accumulation of lipid peroxidation products, which may be one of the causes of sarcopenia." (PMID 33390840, 2021). "In this study, we discovered that SLC7A11 plays a crucial role in the cellular resistance to ferroptosis within the pathological process of sarcopenia." (PMID 40309008, 2025). "Our findings demonstrate that the transcription level of SLC7A11 were markedly lower in sarcopenia samples, reinforcing the role of ferroptosis in the pathophysiology of this condition." (PMID 40309008, 2025). "Our study provides the evidence of GPRC5D-AS1/SLC7A11 dysregulation in human sarcopenia, the clinical sample size (n = 5 per group) and mixed-sex cohorts may limit generalizability." (PMID 40309008, 2025). "Accordingly, this study aims to investigate whether GPRC5D-AS1 influences the occurrence of ferroptosis through the regulation of SLC7A11 expression, thereby significantly affecting the onset and progression of sarcopenia." (PMID 40309008, 2025). "In our experiments, SLC7A11 was significantly downregulated in sarcopenia samples." (PMID 40309008, 2025). "In this study, we focused on the impact of GPRC5D-AS1 on ferroptosis within a cellular model of sarcopenia, but the role of SLC7A11 in this process remains unclear." (PMID 40309008, 2025). "In the sarcopenia group, both GPRC5D-AS1 and SLC7A11 expression levels decreased significantly, along with SLC7A11 protein translation." (PMID 40309008, 2025). "In this study, we systematically explored the relationship between GPRC5D-AS1 and SLC7A11, as well as their roles in HSKM and sarcopenia." (PMID 40309008, 2025).
steatosis (4 papers, 2023 to 2025). Increased lipid within the cytoplasm of cells. "Dietary addition with 10% glycerol only increased TNF-α concentration, steatosis, relative abundances of Escherichia_shigella, Lachnospiraceae_XPB1014_group, Coprococcus, Lactococcus and Megamonas, but decreased SLC7A11 expression in liver of growing-finishing pigs." (PMID 40607347, 2025). "However, supplementation of the mixture with 0.06% Vitamin C and 0.05% niacinamide alleviated steatosis and inflammation in liver of growing-finishing pigs fed diets containing 10% glycerol by reducing the numbers of harmful microbiota and increasing the expressions of CRY1 and SLC7A11." (PMID 40607347, 2025).
atrial fibrillation (3 papers, 2022 to 2025). A disorder characterized by an electrocardiographic finding of a supraventricular arrhythmia characterized by the replacement of consistent P waves by rapid oscillations or fibrillatory waves that vary in size, shape and timing and are accompanied by an irregular ventricular response. "tsRNA-5008a modulates SLC7A11, a marker associated with ferroptosis, through AGO2 targeting, thereby increasing fibrosis and ferroptosis in myocardial tissue, which in turn exacerbates the progression of atrial fibrillation (AF)." (PMID 40001986, 2025).
cervical squamous cell carcinoma (3 papers, 2023 to 2024). A squamous cell carcinoma arising from the cervical epithelium. "Elevated levels of miR-142-5p in HPV16-integrated cervical epithelial cells directly suppress HOXA5, resulting in increased transcription of SLC7A11, which aids in resistance to ferroptosis and the progression of cervical squamous cell carcinoma (CSCC)." (PMID 39420439, 2024).
chromophobe renal cell carcinoma (3 papers, 2021 to 2025). Chromophobe renal cell carcinoma is a rare subtype of renal cell carcinoma, originating from the intercalating cells of the collecting ducts and macroscopically manifesting as a well-circumscribed, highly lobulated, solid tumor that is usually diagnosed at an early stage. "Previous studies have indicated elevated SLC7A11 expression in renal chromophobe cell carcinoma, potentially subject to competitive inhibition by upstream lncRNA." (PMID 39150660, 2025). "Similar to the results of the Oncomine meta‐analysis, SLC7A11 was upregulated in ccRCC, chrRCC (chromophobe renal cell carcinoma), and renal oncocytoma in the GSE15641 dataset." (PMID 34761566, 2021).
gallbladder cancer (3 papers, 2025).
heart failure (3 papers, 2022 to 2024). Inability of the heart to pump blood at an adequate rate to meet tissue metabolic requirements. "In this study, we systematically explored, for the first time, the mechanism by which calycosin alleviates heart failure by inhibiting ferroptosis through the regulation of the Nrf2/SLC7A11/GPX4 signaling pathway." (PMID 39600362, 2024). "Recent studies found that FTH1 knockout mice spontaneously developed heart failure and induced cardiomyocytes ferroptosis through SLC7A11, confirming that the FTH1 is crucial in ferroptosis." (PMID 35677105, 2022).
hematoma (3 papers, 2023 to 2025). A hematoma is a collection of blood from a vascular structure into an extravascular space. "Additionally, the levels of GPX4 and SLC7A11 in the brain tissue around the hematoma were significantly reduced, while the levels of ACSL4 and COX-2 were significantly increased (P < 0.001)." (PMID 39601768, 2025). "Our results demonstrated that DDT reduced hematoma volume, decreased iron deposition, lowered malondialdehyde (MDA) levels, and upregulated glutathione peroxidase (GPX4) and SLC7A11 expression in affected brain regions." (PMID 39525631, 2024).
hemochromatosis (3 papers, 2021 to 2025). A disorder of iron metabolism characterized by a triad of HEMOSIDEROSIS; LIVER CIRRHOSIS; and DIABETES MELLITUS. "Macrophage ferroptosis was first described in hemochromatosis, where iron citrate overload can induce ferroptosis in primary mouse hepatocytes and bone marrow-derived macrophages, accompanied by upregulation of Solute Carrier Family 7 member 11(SLC7A11), increased ROS, and increased nuclear Nrf2." (PMID 41326356, 2025).
Hypertension (3 papers, 2022 to 2025). The presence of chronic increased pressure in the systemic arterial system. "Interestingly, differential methylation at multiple genes (SLC7A11, PHGDH, TXNIP, LOC100132354, CPT1A, SLC1A5) is associated with both AC (this study) and with hypertension." (PMID 34857913, 2022).
Insulin resistance (3 papers, 2023). Increased resistance towards insulin, that is, diminished effectiveness of insulin in reducing blood glucose levels. "SLC7A11 expression is associated with higher insulin sensitivity in muscle and insulin resistance in adipose tissue." (PMID 38288471, 2023). "Similarly, our ITT data showed that overexpression of SLC7A11 improved insulin resistance in HFD mice." (PMID 37984229, 2023). "This could also suggest that immune cells deficient in Slc7a11 might not be able to induce insulin resistance as effectively, although the intrinsically lower insulin secretion does not support this hypothesis." (PMID 37650924, 2023).
invasive breast carcinoma (3 papers, 2024 to 2025). A carcinoma that infiltrates the breast parenchyma. "Within the METABRIC cohort, SLC7A11 CN gain was significantly associated with invasive breast carcinoma of no special type (NST) (p = .0002)." (PMID 38073087, 2024).
Kaposi's sarcoma (3 papers, 2010 to 2021). A malignant neoplasm characterized by a vascular proliferation which usually contains blunt endothelial cells. "SLC7A11 (xCT), which mediates cystine uptake and glutamate efflux, is essential for Kaposi’s sarcoma-associated herpesvirus infection, and it regulates basal levels of extra-synaptic glutamate." (PMID 34436365, 2021).
kidney injury (3 papers, 2022 to 2024). Trauma to the kidney. "Ruscogenin ameliorates acute kidney injury via suppressing ferroptosis in kidney tissues through modulation of the Rev-erbα/β-SLC7A11/HO-1 pathway." (PMID 35845882, 2022). "In a mouse model of folic acid-induced AKI, Rev-erbα/β has been shown to block nuclear transcription of Slc7a11 and HO-1, reduce the inhibitory force of iron death, and direct the development of kidney injury." (PMID 35845882, 2022).
metabolic syndrome (3 papers, 2021 to 2025). A cluster of metabolic risk factors for CARDIOVASCULAR DISEASES and TYPE 2 DIABETES MELLITUS. "In other genes, including SLC7A11 and PHGDH, 17 urate-associated CpGs are associated with conditions defining metabolic syndrome, suggesting that these CpGs may represent a blood DNA methylation signature of cardiometabolic risk factors." (PMID 34887389, 2021).